OR10K1 (olfactory receptor family 10 subfamily K member 1)
Description:
Odorant receptor.
Synonyms: OR1-6
Tractability: Antibody: UniProt places it where antibodies can reach, with medium confidence; UniProt predicts a signal peptide or a membrane-spanning region; its Gene Ontology location is reachable by antibodies, with medium confidence.
Gene: Protein-coding gene on chromosome 1 (158,461,574 to 158,470,857, forward strand). Ensembl gene ENSG00000173285.
Subcellular location: Cell membrane
Pathways (Reactome):
Sensory Perception: Expression and translocation of olfactory receptors
Gene Ontology:
Molecular function: odorant binding; olfactory receptor activity; G protein-coupled receptor activity
Biological process: detection of chemical stimulus involved in sensory perception of smell; G protein-coupled receptor signaling pathway
Cellular component: membrane; plasma membrane
Genetic constraint (gnomAD): Loss-of-function variants: 1 observed, 0.6 expected, observed/expected ratio (o/e) 1.65, 90% interval 0.32 to 1.92. That is too few expected variants to judge how well the gene tolerates losing a copy. Missense variants: 404 observed, 390.53 expected, observed/expected ratio (o/e) 1.03, 90% interval 0.95 to 1.12. Synonymous variants: 186 observed, 160.07 expected, observed/expected ratio (o/e) 1.16, 90% interval 1.03 to 1.31.
Homologues: Orthologues: chimpanzee OR10K1 (97% identical), rabbit OR10K1 (87% identical), guinea pig OR10K1 (84% identical), dog OR10K1 (83% identical), mouse Or10k2 (78% identical), rat Or10k2 (77% identical). Paralogues in human: OR10K2 (82% identical), OR10R2 (57% identical), OR10T2 (52% identical), OR10J1 (50% identical), OR10Z1 (50% identical), OR10J5 (48% identical), OR10J3 (46% identical), OR1L3 (44% identical), OR1L1 (44% identical), OR2A5 (43% identical), OR2A1 (43% identical), OR2A42 (43% identical), and 116 more.
Diseases named in the same sentence as OR10K1 in open-access papers:
OR10K1 is named in the same sentence as 1 disease in open-access papers, as found by Europe PMC text mining. Sharing a sentence is not in itself a finding about the gene and the disease. The quoted sentences say what the papers report.
metastatic tumor (1 paper, 2015). "In contrast, seven other non-synonymous or frameshift mutations (in genes UGT3A2, PLCG1, OR10K1, COL9A1, MAGEA6, CNBD1 and LG14) were detected only in the metastatic tumor, indicating a selection and proliferative advantage of cells with the diverse genotype under sunitinib treatment." (PMID 26474454, 2015).